EGFR (epidermal growth factor receptor)
Diseases named in the same sentence as EGFR in open-access papers (continued):
Sharing a sentence is not in itself a finding about the gene and the disease.
prostate carcinoma (continued). "We identified the regulatory mechanisms of miR-203 interaction with EGFR signaling, and we defined the roles of the miR-203 regulatory pathway in Ras-activated prostate cancer metastasis and tyrosine kinase inhibitors (TKIs) resistance processes." (PMID 25004126, 2014). "In prostate cancer evidence support the link between the activation of RTKs, like the insulin-like growth factor, keratinocyte growth factor, EGFR or HER2, and the transactivation of the AR in the absence of androgens." (PMID 24779793, 2014). "Activation of EGFR signaling pathway leads to prostate cancer bone metastasis; however, therapies targeting EGFR have demonstrated limited effectiveness and led to drug resistance." (PMID 25004126, 2014). "Cross-talk between IGF-1R and EGFR has been reported in breast, lung, and prostate cancer cells as well as in COS cells, which has stimulated interest in understanding the cooperativity between these receptors." (PMID 24904523, 2014). "Though the answer to the discrepancy of Gαs function in different cancers was still unclear, and the role of Gαs in prostate cancer was also in dispute, our results were relatively easy to understand for Gαs had a close relationship with EGFR." (PMID 24741584, 2014). "EGFR belongs to ErbB oncogene family which also includes ErbB-2, 3, and 4 and is comprehensively expressed in epithelial cells including prostate cancer cells." (PMID 24741584, 2014). "We show here that miR-203 expression suppresses bone metastasis and induces apoptosis in TKIs-resistant Ras-activated prostate cancer cells in which miR-203 is down-regulated by EGFR signaling." (PMID 25004126, 2014). "Our results support the existence of a miR-203, EGFR, TKIs resistance regulatory network in prostate cancer progression." (PMID 25004126, 2014). "The EGFR pathway is the dominant regulator of prostate cancer progression, and so we analyzed the regulatory interactions of EGFR ligands with miR-203 and its respective functional roles in TKIs resistance and metastasis." (PMID 25004126, 2014). "Inhibition of SGLT1 sensitizes prostate cancer cells to treatment with EGFR (epidermal growth factor receptor) tyrosine kinase inhibitor." (PMID 25254045, 2014). "Paclitaxel, androgen, and inhibitors for PI3K/Akt, EGFR, Src, or Bcl-2 seem to be potential choices for treatment of advanced prostate cancers." (PMID 24349321, 2013). "A crosstalk between AR and EGFR was previously observed in human hormone-dependent prostate cancer-derived LNCaP cells." (PMID 24130806, 2013). "Previously, transfection of EGFR siRNA into metastatic prostate cancer cells resulted in decreased intracellular glucose levels, whereas treatment with an EGFR kinase inhibitor did not affect intracellular glucose.." (PMID 23531874, 2013). "Recent studies have suggested that EGFR or ERBB2 contribute to prostate cancer (PCa) progression by activating the androgen receptor (AR) under hormone-poor conditions." (PMID 24223781, 2013). "Our observations suggested that Akt, EGFR, Src, Bcl-2, and AR signaling pathways are potential therapeutic targets for AR-positive castration-resistant prostate cancers." (PMID 24349321, 2013). "Our observation suggested that chemotherapy drugs or inhibitor targeting either Akt or EGFR can still be effective to treat advanced prostate cancer even the patient has received androgen ablation therapy for more than 1-2 years." (PMID 24349321, 2013). "The cross-talk between EGFR and AR is important in regulating proliferation of androgen-independent prostate cancer cells." (PMID 24349321, 2013). "Autocrine activation of EGFR is a common feature of prostate cancer cells in contrast to normal prostate epithelial cells." (PMID 24349321, 2013). "For instance, the EGFRvIII mutant and a number of EGFR tyrosine kinase domain mutants that display activated EGFR signaling have been detected in prostate cancer." (PMID 23620784, 2013).
prostate carcinoma (continued). "By investigating DU145 sphere cells, a population of prostate cancer cells with stem-like properties, we report here that epidermal growth factor receptor (EGFR) signaling plays a critical role in the propagation of DU145 PCSCs." (PMID 23620784, 2013). "Treatment of PC-3 human prostate cancer cells with luteolin or BMHPC modulated the expression of a number of genes in the epidermal growth factor receptor signaling pathway (EGFRSP) and cell cycle pathway (CCP)." (PMID 23675277, 2012). "The prognostic relevance of EGFR expression was also observed in a recent Italian series of prostate cancer patients." (PMID 22546016, 2012). "The EGFR, AR and T-cell receptor, as well as several classes of G-protein coupled receptors appeared to be significantly altered during prostate cancer initiation, the transition from primary to metastatic prostate cancer, and in case of disease recurrence." (PMID 23185449, 2012). "Others also described negative regulation of AR expression and activity by EGFR signaling in prostate cancer." (PMID 22922989, 2012). "Specifically, in prostate cancer cells, AR signals upregulate EGFR and ERBB2 gene expression, whereas activation of EGFR and ERBB2 modulates AR functions." (PMID 22922989, 2012). "In prostate cancer, accumulating evidence has indicated that EGFR/ERBB2 signals induce AR transactivation in an androgen-dependent and -independent manner." (PMID 22922989, 2012). "Certain result suggests that anti-invasive effect in androgen-independent prostate cancer by controlling MMP-9 expression through the suppression of the EGFR/JNK pathway." (PMID 22454661, 2012). "We treated the mixture of the cells with two gold conjugates using PSMA (prostate cancer specific) and C225 (anti-epidermal growth factor receptor) antibodies." (PMID 21442036, 2011). "Pralatrexate showed synergistic cytotoxic activity with several classical cytotoxic agents as well as with targeted EGFR inhibitors in the DU-145 prostate cancer line, and further investigation in clinical trials is warranted." (PMID 21179031, 2011). "Constitutive EGFR activation is a common oncogenic signal in prostate cancer as well as in other malignancies." (PMID 22110740, 2011). "For instance EGFR expression is increased in a significant proportion of prostate cancer patients and increased expression correlates with increased risk of relapse and progression to castration resistant disease." (PMID 22193779, 2011). "In contrast, phosphorylation of both ERK and Akt induced by neurotensin was mediated by PKC-dependent EGFR transactivation in prostate cancer cells." (PMID 21961726, 2011). "The present study also analysed and compared the prognostic value of the total expression of EGFR, Her-2 and ErbB3 receptors, as well as their activated forms in a series of primary prostate cancer specimens." (PMID 20216540, 2010). "A number of previous studies have already reported the association of EGFR, Her-2 and ErbB3 with PSA biochemical recurrence in prostate cancer patients." (PMID 20216540, 2010). "The interaction between androgen receptor and EGFR in the caveolae of prostate cancer cells has been recently reported." (PMID 21124760, 2010). "Overexpression of Id1 is associated with progression of prostate cancer and Id1-induced androgen-independent prostate cancer cell growth is correlated with upregulation of EGFR." (PMID 20842131, 2010). "In summary, our multimarker analysis provides evidence that EGFR, Her-2 and ErbB3 are involved in the constitutive activation of Akt and NF-κB, which validates, for the first time in prostate cancer samples, previous in vitro data obtained in cell lines." (PMID 20216540, 2010). "In this study, we sought to extend these in vitro studies by an ex vivo analysis of the determinants of EGFR and Her-2 signalling in NF-κB activation in prostate cancer tissues." (PMID 20216540, 2010).
prostate carcinoma (continued). "Multivariate analysis suggests that EGFR and p65 are two independent prognostic indicators in prostate cancer tissue, which also supports previous reports analysing these two markers separately." (PMID 20216540, 2010). "We analysed a prostate cancer tissue microarray of 63 patients for the expression of total and activated EGFR, Her-2 receptors and the signalling molecules PTEN, phospho-PTEN, Akt, phospho-Akt and the NF-κB subunit p65." (PMID 20216540, 2010). "Regulation of EGFR expression by androgens is shown to be at the transcriptional level, both in normal prostate tissue and prostate cancer (PCa) cell lines." (PMID 19888222, 2009). "The epidermal growth factor receptor family (EGFR/HER1, HER2/neu and HER3)/PI3K/Akt signaling axis has been implicated in prostate cancer development and progression." (PMID 19432987, 2009). "Since growing evidence implicates the HER family in prostate cancer progression, we evaluated the cytotoxic effect of Erlotinib [EGFR/HER1 tyrosine kinase inhibitor (TKI)] on LNCaP cells and demonstrated a cytotoxic effect with an IC50 of >10 μM." (PMID 19432987, 2009). "Suppression of EGFR signaling by EGFR inhibitors is known to reduce the incidence of prostate cancer metastasis to the bone in nude mice models." (PMID 18320059, 2008). "Activation of the EGFR leads to rapid expression of Egr1 in a variety of settings, including prostate cancer cells." (PMID 19032775, 2008). "Studies on prostate cancer, ovarian cancer and renal cell carcinoma showed high Id-1 levels to be correlated with high EGFR levels." (PMID 19014499, 2008). "We have shown that UV irradiation of prostate cancer cells leads to rapid and extensive induction of Egr1 via activation of the EGFR/ERK1/2 pathway and to apoptosis." (PMID 19032775, 2008). "We show, herein, that hepatocytes elicit E-cadherin expression in prostate carcinoma cells concomitant with downregulation of EGFR signalling." (PMID 17406365, 2007). "Previous studies demonstrate activation of the human epidermal growth factor receptor (EGFR) in prostate cancer." (PMID 17662137, 2007). "This was supported by our recent finding that pharmacological abrogation of EGFR signalling in prostate carcinoma cells reverses decreased E-cadherin expression rendering these cells less invasive and more cohesive." (PMID 17406365, 2007). "The two human prostate cancer cell lines, DU145WT and PC3, present autocrine activation of endogenous and exogenous EGFR, as is the norm for prostate carcinoma cells." (PMID 16804520, 2006). "Epidermal growth factor (EGF) receptor (EGFR)-mediated motility, present in both autocrine and paracrine modes in prostate carcinomas, requires de novo transcription to persist over times greater than a few hours." (PMID 16804520, 2006). "EGFR signalling drives motility in fibroblasts and carcinoma cells and invasion of human prostate carcinoma cells." (PMID 16804520, 2006). "The functional consequences of EGFR signalling crossattenuation by Cetrorelix extend to the invasive potential of the prostate carcinoma cells." (PMID 15655536, 2005). "To confirm and extend the inhibitory effects of Cetrorelix on prostate carcinomas, we utilised a genetically engineered human androgen-independent prostate carcinoma cell line that overexpresses a full-length EGFR, DU-145 WT." (PMID 15655536, 2005). "Other LHRH analogues have been shown to limit prostate carcinoma cell growth secondary to downregulation of EGFR or through interference with signalling pathways initiated by the EGFR." (PMID 15655536, 2005). "This subline is highly invasive in response to upregulation of autocrine EGFR signalling that exists in practically all prostate carcinomas." (PMID 15655536, 2005). "Previously, we have shown that DU-145 WT, a subline of the human prostate carcinoma cell line DU-145, presents autocrine EGFR signalling that is critical to both cell proliferation and invasion." (PMID 15655536, 2005).
prostate carcinoma (continued). "Our results support ongoing therapeutic attempts of EGFR inhibition in subgroups of patients with prostate cancer." (PMID 14735192, 2004). "Earlier studies have demonstrated an unexplained depletion of the epidermal growth factor receptor (EGFR) protein expression in prostatic cancer." (PMID 10638988, 2000). "The presence of specific and high affinity epidermal growth factor receptors (EGF-R) has been demonstrated in human prostate cancer (CaP)." (PMID 2478180, 1989). "For prostate cancer, statins may disrupt lipid rafts, which impairs key signalling pathways including the androgen receptor (AR), EGFR, and PI3K–AKT, thereby reducing tumour growth." (PMID 41583365, 2026). "Furthermore, TNS4 is downregulated in paclitaxel-resistant PC-3 and DU145 prostate cancer cells, where its expression negatively correlates with EGFR levels, indicating that TNS4 exerts anti-tumor effects via EGFR inhibition." (PMID 40906372, 2025). "Also, resveratrol can inhibit prostate cancer and of oral squamous cell carcinoma drug resistance by down-regulating EGFR." (PMID 40490812, 2025). "Additionally, silibinin improves radiosensitivity in prostate cancer (DU 145) cells by mitigating DNA damage, particularly following EGFR knockdown." (PMID 40490812, 2025). "Similarly, TNS4 exhibits contradictory effects on EGFR: it stabilizes EGFR in lung/bladder/esophageal cancers but downregulates EGFR in prostate cancer cells." (PMID 40906372, 2025). "Taking advantage of high‐throughput screening approaches and using models of PCa cells mimicking early (PNT2‐ETV1 and PNT2‐ERG) and advanced (LNCaP and VCaP) prostate cancer, we gained better insights into the relevance of the EGFR/STATs pathway for ETS‐driven prostate carcinogenesis." (PMID 40808640, 2025). "AR can upregulate epidermal growth factor receptor expression in prostate cancer cells." (PMID 39917165, 2025). "Moreover, TNS4 negatively regulates EGFR expression in prostate cancer cells, contrasting with findings in other cancers." (PMID 40906372, 2025). "CMTM5-v1 increased EGFR inhibitor’s sensitivity against prostate cancer cells." (PMID 39948411, 2025). "Although the basis for this tissue-specific difference remains unknown, EGFR inhibition likely mediates TNS4’s anti-tumorigenic function in prostate cancer." (PMID 40906372, 2025). "The effective regulation of EGFR pre-mRNA splicing function by USP39 suggests that it may have the potential to become a target for targeted therapy of prostate cancer." (PMID 40672756, 2025). "Cotargeting EGFR and STAT3 with Erlotinib and TTI‐101 impairs both 2D and 3D growth of ETV1‐overexpressing prostate cancer cells by disrupting a self‐sustaining ETV1–EGFR positive feedback loop that promotes EGFR and STAT3 expression and phosphorylation (activation)." (PMID 40808640, 2025). "CMTM5 also suppresses prostate cancer by inactivating the EGFR/PI3K/AKT pathway." (PMID 39166861, 2024). "Moreover, in PTEN-negative prostate cancer cells, plectin binds to actin-rich adhesions, leading to the activation of epidermal growth factor receptor (EGFR)/phosphoinositide 3-kinase (PI3K)/protein kinase B (PKB) and focal adhesion kinase (FAK)/Src pathways." (PMID 39334817, 2024). "Moreover, miR-133a was identified as contributing to the promotion of prostate cancer bone metastasis by downregulation, potentially mediated through its targeting of EGFR and inhibition of the PAM signaling pathway." (PMID 38504785, 2024). "In prostate cancer cells, EGFR was shown to initiate EMT under the control of AKT." (PMID 38672614, 2024). "On the other hand, WFDC2 has been identified as a prominent biomarker in various cancers, including lung, ovarian, and prostate cancers, with roles in tumor metastasis and prognosis due to its interaction with EGFR and its ability to modulate cancer cell migration." (PMID 39296934, 2024). "Additionally, EGFR and PDGFRA mutations were observed in liver, lung, colorectal, and prostate cancers." (PMID 39594421, 2024).
prostate carcinoma (continued). "Using cBioPortal, we also detected a negative correlation between ZNRF3/RNF43 expression and EGFR protein in multiple other cancer types, including prostate cancer where ZNRF3 or RNF43 is deleted or mutated with a rate of 5%." (PMID 38260423, 2024). "Additionally, GABA and GABAAR agonists, such as isoguvacine, were found to enhance epidermal growth factor receptor signaling, thereby promoting the proliferation of PC-3 and LNCaP prostate cancer cells." (PMID 38287309, 2024). "HE4 suppresses prostate cancer metastasis by inactivating EGFR/AKT/GSK3B/Snail signaling pathway." (PMID 38304432, 2024). "AR was suspected in promoting invasiveness of both androgen-dependent and independent prostate cancer; its expression affects EGFR-mediated signaling, and targeting EGFR in androgen-independent prostate cancer could inhibit tumor proliferation and invasion." (PMID 39459070, 2024). "This may have significant clinical significance, as inhibiting EGFR signalling can sensitise prostate cancer cells to chemotherapeutic agents such as Adriamycin." (PMID 39796673, 2024). "We developed new anti-EGFR targeted toxins for the treatment of prostate cancer." (PMID 37859824, 2023). "Moreover, the latest literature also indicated that NRP1 promotes prostate cancer progression via modulating the EGFR-dependent AKT pathway activation." (PMID 37190154, 2023). "Consequently, we focus in this research on development of this hybrid scaffold to selectively inhibit EGFR/HER2 tyrosine kinases as well as to assess the antiproliferative activity of this new series against prostate carcinoma cell lines." (PMID 37096560, 2023). "Anti-SP therapy could strongly suppress cell growth and induce apoptosis in breast, colon, or prostate cancer cell lines and decrease the steady state of Her2 and EGFR." (PMID 37215113, 2023). "Other common essential targets include EGFR in prostate cancer." (PMID 37740463, 2023). "Furthermore, it has been shown that growth factor receptors, including EGFR, cross-talk with androgen receptor in prostate cancer and epithelial cells." (PMID 36879303, 2023). "However, little information regarding the role of endocytosis-mediated receptor regulation for carcinogenic pathways such as EGFR exist, particularly in human tissue and in prostate cancer." (PMID 36869937, 2023). "Moreover, berberine-down-regulated EGFR activation stimulated by EGF led to a reduction in phosphorylated EGFR expression in prostate cancer PC-3 cells, which supported our findings." (PMID 36770659, 2023). "We also hypothesized that there is increased recycling of EGFR in prostate cancer which may be correlated to CME." (PMID 36869937, 2023). "In support of this notion, a recent study highlighted a mechanism by which the interaction of UGT2B28 with the adaptor huntingtin interacting protein 1 triggered epidermal growth factor receptor signaling to promote prostate cancer cell proliferation and invasion." (PMID 37174695, 2023). "Additionally, a recent study found that the overexpression of the epidermal growth factor receptor (EGFR) in prostate cancer cells leads to the upregulation of the ligand for the LIF receptor (LIFR)." (PMID 37601653, 2023). "EGF-PE24mut showed high and specific cytotoxicity in the EGFR-expressing prostate cancer cells." (PMID 37859824, 2023). "In summary, we have revealed a mechanism by which prostate cancer cells switch from hormone-dependent growth mediated through AR signaling to hormone-independent growth mediated through EGFR signaling; in addition, we have identified the key regulator as 3-O-sulfated HS produced by HS3ST1." (PMID 37463954, 2023). "Importantly, DHRS7 expression negatively correlates with EGFR expression and positively with survival rates in prostate cancer patients." (PMID 35804847, 2022).